NBPF11 (NBPF member 11)
Synonyms: NBPF24
Tractability: PROTAC: ubiquitination databases record sites on it.
Gene: Protein-coding gene on chromosome 1 (148,102,042 to 148,152,342, reverse strand). Ensembl gene ENSG00000263956.
Subcellular location: Cytoplasm
Subcellular location (Human Protein Atlas): Cytosol; Primary cilium; Cytokinetic bridge; End piece; Golgi apparatus; Microtubules; Mid piece; Principal piece; Vesicles
Gene Ontology:
Cellular component: cytoplasm
Genetic constraint (gnomAD): Loss-of-function variants: 37 observed, 36.76 expected, observed/expected ratio (o/e) 1.01, 90% interval 0.77 to 1.32. The upper end of that interval is the gene's LOEUF score, 1.32, which puts it in group 5 of 6, group 1 being the genes least tolerant of losing a copy. Missense variants: 373 observed, 350.4 expected, observed/expected ratio (o/e) 1.06, 90% interval 0.98 to 1.16. Synonymous variants: 126 observed, 126.77 expected, observed/expected ratio (o/e) 0.99, 90% interval 0.86 to 1.15.
Homologues: Paralogues in human: NBPF12 (93% identical), NBPF9 (90% identical), NBPF14 (90% identical), NBPF26 (90% identical), NBPF8 (90% identical), NBPF10 (90% identical), NBPF1 (82% identical), NBPF19 (61% identical), NBPF20 (61% identical), NBPF15 (58% identical), NBPF3 (44% identical), NBPF4 (31% identical), and 1 more.
Diseases named in the same sentence as NBPF11 in open-access papers:
NBPF11 is named in the same sentence as 2 diseases in open-access papers, as found by Europe PMC text mining. Sharing a sentence is not in itself a finding about the gene and the disease. The quoted sentences say what the papers report.
neuroblastoma (1 paper, 2015). Neuroblastoma (NB) is the most common solid, extracranial childhood tumor. "Three fast evolving genes (NBPF11, NBPF12 and NBPF15) that are differentially expressed in both sPTB and PE are part of a neuroblastoma breakpoint (NBPF) gene family that has been shown to exhibit neuron-specific expression and copy number variations." (PMID 26641094, 2015).
NBPF11 also shares sentences with these, for which no sentence is quoted: congenital hypothyroidism (1 paper).